SIRT6 (sirtuin 6)
Diseases named in the same sentence as SIRT6 in open-access papers (continued):
Sharing a sentence is not in itself a finding about the gene and the disease.
ovarian carcinoma (25 papers, 2018 to 2025). A malignant neoplasm originating from the surface ovarian epithelium. "Conversely, SIRT6 is downregulated in ovarian cancer tissues, and its low expression is closely associated with tumor infiltration and metastasis." (PMID 38548549, 2024). "Further, the invasiveness of ovarian cancer cells mediated by sirtuin-6 was associated with the expression of EMT-related molecules, such as Snail, E-cadherin, and activated β-catenin." (PMID 32365503, 2020). "In human ovarian carcinomas, the expression of SIRT6 and active β-catenin were associated with advanced clinicopathological factors and shorter survival of patients." (PMID 30524965, 2018). "Our results, in addition to the prognostic significance of SIRT6 expression, there was a significant association between the nuclear/cytoplasmic expression of SIRT6 and the nuclear/cytoplasmic expression of active β-catenin in ovarian cancer tissue samples." (PMID 30524965, 2018). "SIRT6-mediated invasiveness of ovarian cancer cells was associated with the expression of epithelial-to-mesenchymal transition-related signaling molecules such as snail, vimentin, N-cadherin, E-cadherin, and activated β-catenin." (PMID 30524965, 2018). "Consistently, the expression of SIRT6 was associated with the expression of active β-catenin in ovarian cancer cells." (PMID 30524965, 2018). "In human ovarian carcinomas, the expressions of SIRT6 and active β-catenin were associated with higher tumor stage, higher histologic grade, and platinum-resistance." (PMID 30524965, 2018). "Therefore, our results suggest that SIRT6 expression is closely associated with invasiveness of ovarian carcinomas in conjunction with β-catenin expression." (PMID 30524965, 2018). "In addition, SIRT6-mediated invasiveness of ovarian cancer cells was associated with the expression of EMT signaling molecules such as E-cadherin, N-cadherin, snail, vimentin, and active β-catenin." (PMID 30524965, 2018). "SIRT6 expression is significantly reduced in human ovarian cancer tissues compared to normal tissues, and downregulation of SIRT6 enhanced the proliferation of ovarian cancer cells." (PMID 37936548, 2024). "In another part, SIRT6 and SIRT3 are tumor suppressor gene and considered cancer-associated genes and downregulation of SIRT6 has been found to increase ovarian cancer cell growth." (PMID 39349928, 2024). "Downregulation of SIRT6 enhanced the proliferation of ovarian cancer cells, while SIRT6 OE inhibited their growth." (PMID 37936548, 2024). "The expression of SIRT6 in ovarian cancer tissues was significantly higher than that in normal tissues." (PMID 37894746, 2023). "The role of SIRT6 is also controversial in ovarian cancer due to the fact that it is involved in the epithelial-to-mesenchymal transition of ovarian cancer cells." (PMID 37630770, 2023). "SIRT6 promotes the migration and invasion of ovarian cancer cells by inducing mitochondrial fission and promoting the formation of stress fibers." (PMID 37894746, 2023). "This was done to understand the effect of increased SIRT6 in PA1 ovarian cancer cell line instead of comparing the cancer cells directly to the IOSE‐364 cells." (PMID 35686673, 2022). "SIRT6 overexpression exhibited augmented glycolytic rate whereas silencing SIRT6 decreased glycolysis in ovarian cancer cells." (PMID 35686673, 2022). "Through qPCR experiments and histology studies, we configured the increased level of SIRT6 in ovarian cancer cells (PA1) as well as in patients' tissues." (PMID 35686673, 2022). "Overall, our study puts forward the tumor‐promoting function of SIRT6 in ovarian cancer cell lines and high‐grade patient samples." (PMID 35686673, 2022). "Ovarian cancer cells (PA1) overexpressing SIRT6 were found to show unaltered proliferation depicted by the unchanged expression of the cell proliferation markers PCNA and Ki‐67." (PMID 35686673, 2022).
ovarian carcinoma (continued). "Our data indicated a higher expression of SIRT6 in ovarian cancer tissues compared with the non‐malignant ovarian tissue." (PMID 35686673, 2022). "Among sirtuin orthologs, SIRT6 emerges as an important oncogenic player, although its possible mechanistic involvement in ovarian cancer advancement is still elusive." (PMID 35686673, 2022). "siRNA‐mediated downregulation of SIRT6 was found to decrease cellular invasion through compromised mitochondrial fragmentation and subsequent reduction in stress fiber formation in ovarian cancer cells." (PMID 35686673, 2022). "Further, we observed that overexpression of SIRT6 enhances glycolysis and oxidative phosphorylation in ovarian cancer cells." (PMID 35686673, 2022). "To screen the effect of SIRT6 on glycolysis in ovarian cancer cells, we performed extracellular flux analysis and found that SIRT6 overexpression had significantly increased glycolysis and glycolytic reserve in PA1 cells." (PMID 35686673, 2022). "In ovarian cancer, SIRT6 knockdown in OVCAR3 and OVCAR5 ovarian cancer cells significantly inhibited cell migration and invasion." (PMID 35463332, 2022). "The authors reported that SIRT6 expression (at the mRNA and protein levels) was significantly reduced in human ovarian cancer tissues compared to normal tissues." (PMID 33435147, 2021). "In liver, lung, pancreas, colon, and ovarian cancers, SIRT6 is downregulated in tumors, and/or the higher SIRT6 expression is associated with longer overall survival." (PMID 34244565, 2021). "The anti-proliferative effect of SIRT6 on ovarian cancer cells is related to Notch 3 signaling pathway, which is involved in tumor progression of ovarian carcinoma." (PMID 31591350, 2019). "SIRT6 inhibits ovarian cancer cell proliferation via Notch3 downregulation, and correlates with ovarian carcinoma prognosis." (PMID 30064416, 2018). "In this study, we evaluated the expressions of SIRT6 and active β-catenin in human ovarian carcinomas and ovarian cancer cells." (PMID 30524965, 2018). "In this study, we evaluated the expression and roles of SIRT6 in conjunction with the expression of active β-catenin in 104 human ovarian carcinomas and ovarian cancer cells." (PMID 30524965, 2018). "In OVCAR3 and OVCAR5 ovarian cancer cells, knock-down of SIRT6 significantly inhibited the migration and invasion of cells, but did not inhibit the proliferation of cells." (PMID 30524965, 2018). "In human ovarian carcinomas, immunohistochemical expression of SIRT6 and β-catenin was observed in both the cytoplasm and the nuclei of tumor cells." (PMID 30524965, 2018). "Clinicopathological variables and expression of SIRT6 and active β-catenin in 104 ovarian carcinomas." (PMID 30524965, 2018). "However, contrasting evidence from another study showed that SIRT6 overexpression enhanced glycolysis and promoted mitochondrial fragmentation in ovarian cancer cells, processes that facilitate metastasis." (PMID 41471349, 2025). "A study examining the correlation between sirtuin expression and treatment outcomes found that SIRT4 and SIRT6 had significant prognostic value for both overall survival and progression-free survival, suggesting their potential roles as tumor suppressors in ovarian cancer." (PMID 41471349, 2025). "Their studies showed that exosomes from ovarian cancer cell lines carrying PANDAR increased the SIRT4/SIRT6 mRNA proportion in ovarian cancer cells by interacting with the target gene SRSF9, significantly enhancing tumor cell survival and chemotherapy resistance in vitro." (PMID 39334866, 2024). "Moreover, SIRT6 and active β-catenin expressions were correlated with higher histologic grades, tumor stages, and platinum resistance in human ovarian carcinomas." (PMID 38203666, 2023). "Therefore, increased SIRT6 expression has been found to promote the invasiveness of ovarian cancer cells." (PMID 35686673, 2022). "SIRT6 is highly expressed in ovarian cancer cells and regulates tumor cell invasion." (PMID 35686673, 2022).
ovarian carcinoma (continued). "Thus, the present report establishes the impact of SIRT6 in the regulation of morphological and functional aspects of mitochondria that modulates invasion in ovarian cancer cells." (PMID 35686673, 2022). "Therefore, our observations revealed an important role of SIRT6 in the regulation of mitochondrial morphology and how this facilitates ovarian cancer invasion." (PMID 35686673, 2022). "SIRT6 enhances the glycolytic rate and oxidative phosphorylation in ovarian cancer cells." (PMID 35686673, 2022). "believe that SIRT6 is overexpressed in ovarian cancer tissues." (PMID 36505774, 2022). "SIRT6 promotes mitochondrial fission and subsequent cellular invasion in ovarian cancer." (PMID 36505774, 2022). "Accordingly, we found an enhanced rate of basal respiration by SIRT6 in ovarian cancer cells." (PMID 35686673, 2022). "However, there was a marked elevation in cell invasion properties in both PA1 and SKOV3 ovarian cancer cells on SIRT6 overexpression, which was found to decrease subsequently on SIRT6 knockdown." (PMID 35686673, 2022). "Transcriptomics data revealed the effect of SIRT6 on majorly three groups viz., cancer, metabolism, and mitochondria, which gave us an indication as to how it may modulate ovarian cancer." (PMID 35686673, 2022). "However, the expression of SIRT6 in human ovarian cancer tissues was significantly decreased, and the expression of Notch3 was increased, which further promoted the development of cancer." (PMID 35463332, 2022). "To decipher the biological significance of SIRT6 in ovarian cancer, we checked the expression of SIRT6 in patients' tissue sections and found a significant increase of SIRT6 in high‐grade serous ovarian cancer tissues (HGSOC) compared to that in non‐cancer ovarian sections." (PMID 35686673, 2022). "Beyond that, the MAPK signaling pathway also modulates glycolysis and this could be the reason for the increased cellular glycolysis on SIRT6 overexpression in ovarian cancer cell lines." (PMID 35686673, 2022). "The lack of direct evidence regarding the exact role of SIRT6 in ovarian cancer progression led us to decipher its association in driving ovarian cancer cell invasion." (PMID 35686673, 2022). "Moreover, SIRT6 overexpression in ovarian cancer cells inhibits proliferation and the expression of Notch3, a prognostic factor for ovarian serous carcinoma." (PMID 33800266, 2021). "In addition, they revealed that SIRT6 suppressed the expression of Notch 3 through downregulation of its expression both at the mRNA and protein levels in ovarian cancer cells." (PMID 33435147, 2021). "Furthermore, they showed that overexpression of SIRT6 inhibited the proliferation of ovarian cancer cells SKOV3 and OVCAR3." (PMID 33435147, 2021). "For the analysis of the gene expression association with their promoter DNA methylation in ovarian cancer cell lines, our results showed that SIRT4 had significantly fewer methylations than does SIRT6, but there was one cell line that had up to 0.2 correlation more than others." (PMID 34335684, 2021). "By contrast, down-regulation of SIRT6 enhanced ovarian cancer cell growth." (PMID 33435147, 2021). "Another possible novel therapeutic target for ovarian cancer therapy is SIRT6." (PMID 33435147, 2021). "Some studies indicated that SIRT6 could inhibit ovarian cancer cell growth and was a favorable prognostic factor." (PMID 31113446, 2019). "Indeed, SIRT6 overexpression inhibited the proliferation of ovarian cancer cells, whereas SIRT6 downregulation enhanced cell growth." (PMID 31591350, 2019). "However, Notch 3 overexpression blocked this anti-proliferative effect of SIRT6 in ovarian cancer cells." (PMID 31591350, 2019). "However, additional evidence for the role of SIRT6 as a tumor suppressor in ovarian cancer has also been published, showing that SIRT6 expression is significantly reduced in human ovarian cancer tissues compared to normal tissues." (PMID 31591350, 2019).
ovarian carcinoma (continued). "However, the role of SIRT6 in tumorigenesis has been controversially reported and the studies on the role of SIRT6 in ovarian cancers is limited." (PMID 30524965, 2018). "Moreover, SIRT6 mediated increase of invasiveness of ovarian cancer cells was attenuated by knock-down of β-catenin." (PMID 30524965, 2018). "Therefore, further study is needed to clarify the role(s) of SIRT6/β-catenin signaling in the progression of ovarian cancers." (PMID 30524965, 2018). "Therefore, to evaluate the relationship between SIRT6 and β-catenin in the invasiveness of ovarian cancers, we co-transfected a SIRT6 overexpression vector and shRNA for β-catenin." (PMID 30524965, 2018). "As a tumor suppressor, SIRT6 is downregulated in ovarian cancer." (PMID 30064416, 2018). "However, despite the limited role of SIRT6 in ovarian cancer cells, SIRT6 showed a significant prognostic role in human ovarian carcinomas." (PMID 30524965, 2018). "Moreover, nuclear expression of SIRT6 and active β-catenin were independent indicators of poor prognosis in both the overall ovarian carcinomas and high-grade serous carcinomas." (PMID 30524965, 2018). "When considering the diverse roles of SIRT6 in cell biology and tumorigenesis, SIRT6 might be a potential therapeutic target in ovarian cancers." (PMID 30524965, 2018). "The role of SIRT6 in ovarian cancers has been limited to the invasiveness of cancer cells." (PMID 30524965, 2018). "In conclusion, although there are controversial reports on the role of SIRT6 in human malignant tumors, this is the first study to demonstrate that SIRT6 is involved in the invasiveness of ovarian cancers in a mechanism involving the expression of active β-catenin and EMT signaling." (PMID 30524965, 2018). "Therefore, our results suggest SIRT6 and active β-catenin expression as indicators of poor prognosis for ovarian carcinomas." (PMID 30524965, 2018). "Therefore, based on our previous study, we investigated the expression patterns and roles of SIRT6 and active (de-phosphorylated) β-catenin in human ovarian carcinomas and ovarian cancer cells." (PMID 30524965, 2018). "Moreover, our results indicate nuclear expression patterns of SIRT6 and active β-catenin to be important prognostic indicators of ovarian cancers, especially in high-grade serous carcinomas." (PMID 30524965, 2018). "Therefore, we further evaluated the effects of SIRT6 expression on the proliferation and invasiveness of ovarian cancer cells." (PMID 30524965, 2018). "In 104 ovarian carcinomas, the variables included in the multivariate analysis were age, tumor stage, tumor size, presence of ascites, bilaterality of the tumor, histologic grade, Nu-SIRT6 expression, Cy-SIRT6 expression, Nu-Aβ-catenin expression, and Cy-Aβ-catenin expression." (PMID 30524965, 2018). "Therefore, our results suggest that SIRT6 is involved in the progression of ovarian carcinomas and that inhibition of SIRT6 might be a new therapeutic stratagem for the treatment of ovarian cancers, especially in the cancers with high expression of SIRT6." (PMID 30524965, 2018). "In 104 ovarian carcinomas, the factors significantly associated with both OS and RFS in univariate analysis were age of patients, tumor stage, presence of ascites, serum level of CA125, histologic grade, and the expression of Nu-SIRT6, Nu-Aβ-catenin, and Cy-Aβ-catenin." (PMID 30524965, 2018). "It seemed that SIRT6 and SIRT7 displayed both oncogenic and tumor-suppressive properties in ovarian cancer." (PMID 31113446, 2019). "SIRT6 knockdown inhibited the migration and invasion of ovarian cancer (OC) cells OVCAR3 and OVCAR5, but did not suppress cell proliferation." (PMID 38203666, 2023). "Ovarian cancer cell lines with the SIRT6 knockout gene inhibited migration and invasion without affecting proliferation." (PMID 37630770, 2023). "Increasing SIRT6 expression promotes the invasiveness of ovarian cancer cells but does not alter cellular proliferation." (PMID 36505774, 2022).
ovarian carcinoma (continued). "In ovarian cancer tissues, SIRT6 expression levels are lower than in the non-transformed counterparts." (PMID 33800266, 2021). "Despite the role of SIRT6 on the expression of active β-catenin, SIRT6 did not influence the proliferation of ovarian cancer cells." (PMID 30524965, 2018). "In OVCAR3 and OVCAR5 ovarian cancer cells, knock-down of SIRT6 with shRNA for SIRT6 or overexpression of SIRT6 did not influence the proliferation of cells in the counting of cells, MTT, BrdU incorporation, and colony-forming assays." (PMID 30524965, 2018). "However, knock-down of SIRT6 significantly inhibited migration and invasive activity of both OVCAR3 and OVCAR5 ovarian cancer cells." (PMID 30524965, 2018). "In our ovarian carcinomas, platinum resistance was seen in 70% (14 of 20) of Nu-SIRT6-positive patients, but platinum resistance was only 30% (6 of 20) in Nu-SIRT6-negative patients." (PMID 30524965, 2018). "However, despite extensive studies regarding the role of SIRT6 in human cancers, there has been no report investigating the role of SIRT6 in ovarian cancers." (PMID 30524965, 2018). "The overexpression of SIRT6 did not influence the proliferation of ovarian cancer cells." (PMID 30524965, 2018). "Therefore, when considering EMT as one of the molecular hallmarks of cancer progression, the prognostic significance of SIRT6 and active β-catenin expression might be related with their roles in EMT of ovarian carcinomas." (PMID 30524965, 2018). "The nuclear and cytoplasmic expression patterns of SIRT6 and active β-catenin were classified into negative or positive based on the highest predictive points to estimate survival of ovarian carcinoma patients by receiver operating characteristic curve analysis." (PMID 30524965, 2018). "Although the exact mechanism is not clear, these findings suggest that the role of SIRT6 on β-catenin signaling might be restricted to the invasiveness of ovarian cancer cells." (PMID 30524965, 2018). "Notably, many ovarian cancer cell lines did not have any SIRT4 promoter methylation, where SIRT6 showed the opposite manner." (PMID 34335684, 2021).